IL17A (interleukin 17A)
Diseases named in the same sentence as IL17A in open-access papers (continued):
Sharing a sentence is not in itself a finding about the gene and the disease.
psoriasis (continued). "In a imiquimod psoriasis model, psoriatic inflammation increased brain IL-17A levels; administration of both peripheral anti-IL17A agents and NFκB and p38MAPK inhibitors decreased brain cytokines as well as IL17A-induced depression-like behaviours." (PMID 39959848, 2025). "A new therapeutic antibody, bimekizumab, which blocks both IL-17A and IL-17F, is approved for the treatment of severe psoriasis and currently being tested for its effect on HS." (PMID 41142785, 2025). "Secukinumab, a fully human monoclonal antibody (IgG1) targeting interleukin-17A (IL-17A), a pro-inflammatory cytokine central to the pathogenesis of systemic inflammatory diseases such as psoriasis, represents a significant advancement in therapy." (PMID 39860484, 2025). "In cases of ixekizumab-induced urticaria, IL-17A+ mast cells were found in the skin, which correlated with early relapses of psoriasis after discontinuing the drug." (PMID 39859462, 2025). "Beyond cytokines and B cells, the CARIMA trial investigated secukinumab, an IL-17A inhibitor, in psoriasis patients." (PMID 40727466, 2025). "The impact of IL-17A on psoriasis is modest by itself, but its significant influence in the disease’s development and progression is enhanced through synergy with TNF-α, IL-22, and IFN-γ." (PMID 40303401, 2025). "In this study, we assess the efficacy of AIDEN-IL17, a variant designed to secrete single-chain variable fragments targeting interleukin-17A (IL-17A), in murine models of psoriasis and inflammatory bowel disease." (PMID 41421354, 2025). "To validate the scRNAseq findings that CCR6+ epidermal γδ T cells produce IL-17A during psoriasis, we examined IL-17A production in vivo using IL-17A GFP reporter mice." (PMID 40073267, 2025). "T helper 17 (Th17)/IL-23 axis: Psoriasis is driven largely by IL-23–induced Th17 cells producing IL-17A/F and other cytokines." (PMID 40861474, 2025). "In psoriasis, persistent stimulation of Th17 cells results in excessive production of IL-17A and IL-23, which promote keratinocyte proliferation, angiogenesis, and leukocyte recruitment to the skin." (PMID 41465136, 2025). "The increasing release of inflammatory cytokines, including IL-6, IL-17A, IL-22, IL-23, and TNF-a, by immune cells causes the worsening of epidermal symptoms and ultimately aggravating the psoriasis condition." (PMID 40807399, 2025). "IL-17A has been demonstrated to induce ROS production, contributing to endothelial dysfunction and vascular inflammation in psoriasis-like conditions." (PMID 40137170, 2025). "Anti–IL-17A blockade therapy has shown clinical benefits for psoriasis patients and has recently been approved by the Food and Drug Administration for use in plaque psoriasis." (PMID 40749055, 2025). "We examined the expression of cytokines previously reported to be involved in psoriasis, and found that IL17A, IL26, and CXCL13 were specifically expressed by CD8+ TRM17 and Cycling CD8+ TRM17." (PMID 41162356, 2025). "It has been established that the most critical signaling in psoriasis is mediated by a receptor activated by two cytokines, IL-17A and IL-17F, with IL-17A displaying a stronger effect." (PMID 39859462, 2025). "Although IL-17A-neutralizing antibodies like secukinumab, ixekizumab, and brodalumab are approved for psoriasis treatment, only secukinumab has been clinically tested for MS." (PMID 40141149, 2025). "The blockade of the interleukin (IL)‐17 signalling pathway has revolutionized the treatment of psoriasis with agents such as ixekizumab, and secukinumab (IL‐17A inhibitors), brodalumab (IL‐17 receptor inhibitor) and bimekizumab (IL‐17A and IL‐17F inhibitor)." (PMID 39665153, 2025). "Specifically in psoriasis, IL-17A has been shown to promote metabolic reprogramming of keratinocytes towards increased glycolysis and lipid uptake, associated with increased ROS production." (PMID 40137170, 2025).
psoriasis (continued). "Ixekizumab is a recombinant humanized IgG4 monoclonal antibody that selectively binds to interleukin-17A (IL-17A), a proinflammatory cytokine pivotal in the pathogenesis of psoriasis." (PMID 39941503, 2025). "The synthesized stereoisomer analogues were further evaluated for their cellular efficacy and potency in the treatment of psoriasis by inhibiting the secretion of cytokine IL-17A." (PMID 40299638, 2025). "In particular, the ssDNA aptamer M2, which targets IL17A, has shown potential therapeutic effects in psoriasis models." (PMID 41477217, 2025). "In this superimposed linear psoriasis case, classical psoriatic lesions responded to interleukin (IL)-23 inhibitors, with further improvement following dual IL-17A/F inhibition by bimekizumab." (PMID 40539143, 2025). "As expected, LINC01206 expression was significantly upregulated in NHEK cells following IL‐17A stimulation, consistent with its expression pattern in clinical psoriasis samples." (PMID 40670887, 2025). "Interleukin 12/23 inhibitors, along with IL-17A blockers and IL-17 receptor antagonists, have recently revolutionized psoriasis treatment, and further investigations are ongoing to expand upon this therapeutic advancement." (PMID 40893809, 2025). "Several key cytokines, including TNF-α, IL-12/IL-23, and IL-17A, play a crucial role in the pathogenesis and development of psoriasis." (PMID 40520230, 2025). "IL-17 is known to play a major role in the pathogenesis of psoriasis, and both anti-IL17A and anti-IL17RA antibodies have shown promising results in the treatment of psoriasis." (PMID 40895565, 2025). "With respect to hBD-2 concentration, the positive regulatory role exerted by IL-17 on hBD-2 has been demonstrated; for example, high levels of hBD-2 correlate with low IL-17A levels and increased severity of psoriasis and/or RA." (PMID 40062148, 2025). "In parallel, IDMF suppresses NF-κB, AP-1, IRF1, and STAT-linked pathways, thereby downregulating IL-17A, IL-23A, IL-36G, IFN-γ, and other psoriasis-associated cytokines at their transcriptional origins." (PMID 41465291, 2025). "Although reported results vary, it is generally assumed that serum levels of proinflammatory cytokines, such as TNF-α, IFN-γ, IL-6, IL-8, IL-12, IL-17A, IL-18 and IL-22, are elevated in patients with psoriasis and correlate with disease severity." (PMID 40584532, 2025). "When dysregulated, IL-17a contributes to the pathogenesis of diverse inflammatory and autoimmune conditions, such as in psoriasis, psoriatic arthritis, ankylosing spondylitis, and multiple sclerosis." (PMID 41310729, 2025). "Preclinical studies targeting epidermal Peli1 reduced IL-17A production by skin-resident T17 cells, improving psoriasis-like dermatitis." (PMID 40948748, 2025). "Bimekizumab, a dual IL-17A and IL-17F inhibitor, has shown superior efficacy in psoriasis compared with existing IL-17 inhibitors." (PMID 40429269, 2025). "According to clinical trials, the dual neutralization of IL-17A and IL-17F provides a more prominent suppression of inflammation, resulting in a more significant improvement in clinical outcomes in psoriasis than IL-17A inhibitors." (PMID 40277935, 2025). "Elevated expression of Gls1 in psoriasis promotes the expression of IL-17A by enhancing histone acetylation at the Il17a promoter." (PMID 40956613, 2025). "A pivotal finding demonstrates the critical role of autophagy dysfunction in psoriasis, wherein IL-17A mediates autophagy suppression via the PI3K/AKT/mTOR pathway, establishing a fundamental link between inflammatory signaling and cellular homeostasis." (PMID 40332377, 2025). "Current research focuses on the phytochemical and pharmacoinformatics analysis of VT oil preparation to elucidate its potential against key inflammatory proteins (TNF-α, IL-17A) involved in psoriasis." (PMID 40892753, 2025).
psoriasis (continued). "Targeting Nrf2 to decrease mitochondrial OXPHOS-driven oxidative stress in keratinocytes has been reported to attenuate IL-17A-induced psoriasis by regulating the bioenergetic metabolism." (PMID 41385507, 2025). "This case highlights the potential utility of dual IL-17A/F inhibition in treating this rare and difficult-to-manage psoriasis subtype and suggests a need for further clinical evaluation in larger patient populations." (PMID 40539143, 2025). "For instance, IL-36 and IL-17C mainly act synergistically to enhance tissue inflammation; overexpression of IL-20 can lead to epidermal changes characteristic of psoriasis; and IL-19 potentiates the effects of IL-17A via a positive feedback mechanism." (PMID 40303401, 2025). "In contrast, Arg1 overexpression was observed in lupus erythematosus, seborrheic dermatitis, and psoriasis due to the varying degrees of involvement in dysregulation of Th17/IL‐17A." (PMID 39665264, 2025). "IL-17 inhibitors, which are monoclonal antibodies targeting IL-17A or its receptor, have shown remarkable effectiveness in the treatment of psoriasis." (PMID 40959061, 2025). "Nonetheless, despite the protective function of IL-17, individuals receiving monoclonal antibody therapy aimed at IL-17A or its receptor for psoriasis have exhibited a heightened occurrence of Candida infections." (PMID 40690118, 2025). "In a support vector machine classifier comparing psoriasis and healthy transcriptomes, the CXCL13 showed comparable or superior accuracy to IL17A as an indicator of psoriasis severity." (PMID 41169094, 2025). "IL-17 monoclonal antibodies that block IL-17a (e.g., secukinumab) are currently in clinical practice to treat autoimmune conditions such as psoriasis and psoriatic arthritis." (PMID 41031886, 2025). "IL-23 also stimulates T cells to produce IL-17A, IL-17F, and IL-22, which are key effector cytokines in the pathogenesis of psoriasis, activating and proliferating keratinocytes." (PMID 41376622, 2025). "ASO-210-loaded UCMSC-exosomes reduced psoriasis symptoms, exhausted Th17 cells and reduced enrichment of proinflammatory cytokines, such as IL-17A, IFN-γ, IL-6 and TNF-α, in both spleen and skin lesions in vivo." (PMID 39861699, 2025). "CCL20 (also known as MIP-3α) acts as a chemotactic factor that, through binding with its receptor CCR6, is crucial for transporting IL-17A-producing T cells from the bloodstream to the skin during the progression of psoriasis." (PMID 39861704, 2025). "Neutrophil-derived IL-1β plays a central role in the psoriasis model, promoting IL-17A production through an estrogen receptor-dependent mechanism." (PMID 40948748, 2025). "At week 16, psoriasis area severity index (PASI) value improvement correlated with the reduction of plasmatic levels of IL-17A, IL-17F, and IL-22." (PMID 39861739, 2025). "Psoriasis-associated inflammatory cytokines (e.g., TNF-α, IL-17A, IL-23) and Th17 cells can compromise the blood-brain barrier (BBB)." (PMID 41357183, 2025). "In psoriasis, curcumin exhibits its anti-inflammatory effects by reducing the expression of cytokines such as interleukin-17A (IL-17A), interleukin-17F (IL-17F), interleukin-22 (IL-22), IL-6, IL-1β, and TNF-α, and by inhibiting NF-κB activation." (PMID 40718452, 2025). "Dysregulated Th17 cell activity and increased IL-17A levels are involved in the pathogenesis of autoimmune diseases characterized by chronic inflammation, including psoriasis (PsO), psoriatic arthritis (PsA), MS, and rheumatoid arthritis (RA)." (PMID 40141149, 2025). "IL-17A is the key driver of the pro-inflammatory keratinocyte pathogenesis in psoriasis, along with a dominant IFNγ/STAT1 signature." (PMID 39843435, 2025). "Our results show that protein levels of multiple proteins (32/71) were upregulated at baseline in the lesional skin compared to non‐lesional skin, including three key biomarkers of the psoriasis disease pathology (IL‐17A, CCL20 and TNFα)." (PMID 40970551, 2025).
psoriasis (continued). "Topical application of 1% tapinarof cream alleviated psoriasis symptoms and reduced IL-17A expression in wild-type mice." (PMID 40574044, 2025). "In chronic inflammatory skin disorders such as psoriasis and atopic dermatitis, overexpression of IL-17A/F exacerbates endothelial dysfunction and arterial stiffness, thereby accelerating atherosclerosis." (PMID 40959491, 2025). "AD-MSCs have immunomodulatory potential in the treatment of psoriasis by inhibiting the production of Th17-related cytokines, such as IL-17A and TNF-α, which alleviates imiquimod (IMQ)-induced skin pathological changes associated with psoriasis in mice." (PMID 40427630, 2025). "Overactivation of Treg/Th17 cells accelerates psoriasis progression by releasing various inflammatory factors, such as IL-23, IL-17A, IL-22, IL-6, and IFN-α." (PMID 41425939, 2025). "Recent genetic analyses suggest a bidirectional relationship between psoriasis and depression, potentially mediated by IL-17A, a cytokine elevated in major depressive disorder." (PMID 40428224, 2025). "Ixekizumab is a monoclonal antibody with high affinity and specificity to anti‐interleukin (IL)‐17A, a key pro‐inflammatory cytokine in the pathogenesis of psoriasis." (PMID 40079483, 2025). "This genotype-dependent dysregulation likely arises from altered VDR-mediated transcriptional control of IL17A and IL23A loci, implicating VDR polymorphisms as modifiers of IL-23/Th17 axis hyperactivity in psoriasis pathogenesis." (PMID 40681996, 2025). "Although reverse translational immunology from clinical trials shows the involvement of both IL-17A and IL-17F in psoriasis, the situation in the skeleton is less clear." (PMID 41322402, 2025). "Results showed that IFN-γ, TNF-α, IL-1β, IL-6, IL-17A, IL-18, and IL-23 in psoriasis patients had significantly higher levels compared to controls and a strong correlation between PASI scores and these cytokines." (PMID 40699767, 2025). "In recent years newer therapies have focused on key cytokines in psoriasis pathogenesis, in particular on IL- 23 and IL-17A." (PMID 40141770, 2025). "Monoclonal antibodies directed against either IL-17A or IL-23 have been demonstrated to be efficacious in both psoriasis patients and in spondyloarthropathies." (PMID 39820614, 2025). "IL-17A inhibitors and the IL-23 inhibitor demonstrated significant efficacy in improving both nail and skin lesions in psoriasis." (PMID 40264783, 2025). "The IL-17 family, particularly IL-17A, plays a pivotal role in psoriasis by acting as a pro-inflammatory factor that induces the expression of chemokines and cytokines, recruits neutrophils and monocytes, and drives inflammation." (PMID 40303401, 2025). "In the present study, molecular docking was performed to evaluate the binding affinities of key phytoconstituents from E. neriifolia against interleukin‐17A (IL‐17A; PDB ID: 5HI4), a major cytokine implicated in psoriasis pathogenesis." (PMID 41416116, 2025). "Nowadays, secukinumab—an anti-IL17A biologic agent—is considered an effective and safe treatment for moderate-to-severe psoriasis." (PMID 40861231, 2025). "Psoriasis and psoriatic arthritis (PsA) are IL-23 → IL-17A/F-driven disorders with neutrophil-skewed chemokines (CXCL1/8) and stromal activation." (PMID 41440484, 2025). "Research has shown that resveratrol is able to attenuate imikimod (IMQ)-induced psoriasis-like dermatitis in mice by reducing IL-17A and IL-19." (PMID 40574044, 2025). "For instance, paradoxical Behçet’s disease—characterized by recurrent oral and genital ulcers—has been reported in patients undergoing treatment with IL-17A inhibitors like ixekizumab and secukinumab for psoriasis or other immune-mediated diseases." (PMID 41010307, 2025). "Upon exposure to psoriasis-related autoantigens or environmental triggers (e.g., infection or trauma), these IL-17-producing cells release pro-inflammatory cytokines such as IL-17A/F, TNF, IL-26, and IL-29." (PMID 41226338, 2025).
psoriasis (continued). "These cells synergize with IL-17A-producing Th17 cells to sustain joint damage; CXCL10 specifically associates with PsA development in psoriasis patients." (PMID 41009491, 2025). "Recent studies emphasize the pivotal role of T helper Th-17 and Th-1 cells in the pathogenesis of psoriasis, with interleukin IL-17A, IL-23, and tumor necrosis factor-alpha (TNF-α) serving as central mediators of skin inflammation." (PMID 40748586, 2025). "In conclusion, we demonstrated that TP treatment alleviated IMQ-induced psoriasis-like symptoms in a mouse model and inhibited IL-17A-induced proliferation and inflammation in HaCaT cells." (PMID 40365308, 2025). "Cases of drug-induced lupus after treatment for ankylosing spondylitis and psoriasis with IL-17A inhibitors have also been reported, highlighting the complex role of IL-17 in lupus pathogenesis." (PMID 39940698, 2025). "In three ixekizumab trials in psoriasis, depression remitted in up to 45% of comorbid patients following IL-17A treatment, however mood improvement was only weakly associated with CRP reduction (r = 0.11, p < 0.001)." (PMID 39959848, 2025). "In the present study using IMQ-induced psoriasis, IL-17 A-producing γδ T cells were increased in the skin of mPGES-1−/− mice." (PMID 40481552, 2025). "Background/Objectives: Psoriasis is currently treated with biologics targeting the IL-17A signaling, which plays a major role in immune response and keratinocyte hyperproliferation." (PMID 41153404, 2025). "Inhibitors of IL-17A and its receptor have emerged as important targets for the treatment of autoimmune diseases (such as rheumatoid arthritis, psoriasis, etc.)and inflammatory bowel diseases." (PMID 40070478, 2025). "Accordingly, developing a broad-spectrum ACC1 inhibitor to limit the IL-17A-producing capacity of conventional T cells and γδT17 cells represents a promising therapeutic strategy for psoriasis." (PMID 40360755, 2025). "Another study demonstrated that subcutaneous injection of human umbilical cord MSC exosomes significantly decreased psoriasis-specific cytokines, such as IL-17A and IL-23, and inhibited the phosphorylation of STAT3." (PMID 41007656, 2025). "Secukinumab, a fully human monoclonal antibody that inhibits IL-17A, has shown improvement in vascular endothelial function in psoriasis patients, as demonstrated in the CARIMA study." (PMID 40727466, 2025). "We found a significant reduction in lesional levels of the key psoriasis disease drivers, IL‐23 and IL‐17A, at Week 16 following 20 and 30 mg orismilast, which supports the clinical effect observed in the Phase 2b study." (PMID 40970551, 2025). "This research explores the various phytoconstituents from Euphorbia neriifolia targeting IL‐17A through in silico and in vitro studies for its role in the more precise and effective therapy in Psoriasis." (PMID 41416116, 2025). "The interaction of IL-17A with γδT cells increases proinflammatory IL-17A expression, which in turn triggers psoriasis onset, as well as its progression." (PMID 39903182, 2025). "Monoclonal antibodies against IL-17A and IL-17RA have been developed and proven effective in alleviating psoriasis symptoms." (PMID 40303401, 2025). "Previous studies showed that CCR6+ dermal Vγ4 T cells secrete IL-17A in response to skin damage and during psoriasis." (PMID 40073267, 2025). "Ixekizumab (IXE) is a monoclonal antibody that selectively targets IL-17A, an inflammatory cytokine that plays a critical role in the pathogenesis of psoriasis." (PMID 41158454, 2025). "This indicates that IL-17A inhibitors can, in rare cases, induce a transformation in the type of psoriasis." (PMID 38695018, 2024). "The correlation between the key pathogenic factor IL-17A and abnormal LCFA metabolism in psoriasis patients was further supported using IMQ-treated wild-type (WT) and T-cell receptor delta chain knockout (Tcrd−/−) mice." (PMID 38185620, 2024).